STC2 (stanniocalcin 2)
Diseases named in the same sentence as STC2 in open-access papers (continued):
Sharing a sentence is not in itself a finding about the gene and the disease.
breast carcinoma (continued). "It was found that knockdown of STC2 suppressed the migration of breast cancer cells by Transwell migration assays, and that knockdown of STC2 suppressed breast cancer cells proliferation by inducing cells into cell cycle arrest at G1 phase and augment of cell apoptosis." (PMID 35513366, 2022). "Then we designed and synthesized the siRNA of STC2 to verify the function of STC2 in breast cancer." (PMID 35513366, 2022). "The downstream target gene of LncRNA MAFG-AS1 was STC2 which might promote cell proliferation and metastasis in breast cancer and this study provides a new potential therapeutic target for breast cancer." (PMID 35513366, 2022). "For testing whether STC2 participated in promoting the breast cancer cell proliferation and metastasis mediated by LncRNA MAFG-AS1, rescue experiments were carried out." (PMID 35513366, 2022). "The results showed that STC2 inhibited the proliferation of breast cancer cells and promoted the apoptosis of TNBC cells by inhibiting the phosphorylation of Akt and reducing its phosphorylation level in TNBC cells, thereby blocking the Akt-related signalling pathway." (PMID 35607324, 2022). "However, overexpression of STC2 compromises cell proliferation as well as colony formation in breast cancer cells, suggesting STC2 possesses tumour suppressor-like activities in breast cancer." (PMID 35501821, 2022). "STC2 is co-expressed with Er in breast cancer cell lines and samples." (PMID 35501821, 2022). "STC2 had an unexpectedly high expression in breast cancer tissues with liver metastases." (PMID 37287492, 2021). "However, Jiang’s results indicated that STC2 was over expression in breast cancer tissues and it had a significant effect on lymph node metastasis, distant metastasis, tumor node metastasis (TNM) stage and histological grade." (PMID 37287492, 2021). "Interestingly, favorable effects of STC2 expression in breast cancer were reported in several studies." (PMID 34612765, 2021). "In addition to estradiol, progesterone and retinol acid regulated the expression of STC2 in multiple breast cancer cell lines." (PMID 34612765, 2021). "Our previous study showed that STC2 had little effect on the proliferation of breast cancer cells but could inhibit the invasion and metastasis of breast cancer cells." (PMID 34722511, 2021). "Recently, it has been proved that STC2 is important to the prognosis of breast cancer and people may use it to evaluate breast cancer." (PMID 37287492, 2021). "However, high expression levels of STC2 were found in breast cancer tissues, especially in ER‐positive tissue." (PMID 33788403, 2021). "Esseghir S. and coauthors identified that STC2 was a prognostic marker in breast cancer." (PMID 32258098, 2019). "However, previous studies have also shown that STC2 is upregulated in human gastric cancers, neuroblastomas, breast cancers, colorectal cancers, and renal cell carcinomas." (PMID 27863406, 2017). "Collectively, these results indicate that STC2 may inhibit EMT at least partially through the PKC/Claudin-1-mediated signaling in human breast cancer cells." (PMID 25830567, 2015). "Intriguingly, STC2 had little impact on cell proliferation of breast cancer cells in our study." (PMID 25830567, 2015). "Furthermore, in vivo animal assay showed that STC2 inhibited tumorigenesis and metastasis of breast cancer cells." (PMID 25830567, 2015). "In the present study, by silencing or overexpression of STC2 in aggressive breast cancer cell lines, we found that STC2 might regulate EMT through the activation of Protein Kinase C (PKC)." (PMID 25830567, 2015). "Total PCBs associated with AREG, CYP19A1, ESR2, FOS, KRAS and STC2 genes; PCB 126 associated with AREG, CYP19A1, and STC2 genes and PCB 15 associated with CYP19A1, EGFR, ESR2, FOS, and IGF1 genes overlapped with 17β-estradiol, breast cancer, and endometriosis." (PMID 26512648, 2015).
breast carcinoma (continued). "However, STC2 overexpression in breast cancers, particularly in estrogen receptor-positive breast cancers, is associated with favorable prognoses." (PMID 24606961, 2014). "Hsa-miR-532-5p regulates also stanniocalcin 2 (STC2): it is a glycoprotein hormone that plays an important role in calcium and phosphate homeostasis and is considered a tumor progression predictor for gastric cancer and breast carcinoma." (PMID 24866763, 2014). "Notably, the analysis highlights enrichment in gene sets such as “Vantveer_Breast_cancer_ESR1_Up” and “Hallmarck_Estrogen_Response_Early”, suggesting that STC2 expression is positively correlated with genes upregulated in ER-positive breast cancer and early estrogen response." (PMID 40006048, 2025). "STC2, overexpressed in T cells with a Th2 response, is identified as a metagene that demonstrates negative correlation with immune-associated metagenes in breast cancer." (PMID 35501821, 2022). "Hence, all the results proved that LncRNA MAFG-AS1 could promote breast cancer proliferation and metastasis may partially by up-regulating the expression of STC2." (PMID 35513366, 2022). "Uniquely, STC2 exerted negative effects on tumor development and progression in breast cancer, which may be caused by complexed hormone-dependent mechanisms." (PMID 34612765, 2021). "STC2 may serve as a survival factor for breast cancer cells, contributing to tumor dormancy." (PMID 34612765, 2021). "Moreover, expression of STC2 in human breast cancer correlates with good outcome." (PMID 26951623, 2016). "Thus, STC2 may be exploited as a biomarker for metastasis and targeted therapy in human breast cancer." (PMID 25830567, 2015). "Thus, the function of STC2 in breast cancer is still elusive." (PMID 25830567, 2015). "Furthermore, investigating the role of STC2 in other subtypes of breast cancer, including triple-negative and HER2-positive cancers, could determine whether the findings are broadly applicable across breast cancer subtypes or specific to luminal A and ER-positive patients." (PMID 40006048, 2025). "To further elucidate the role of STC2 in luminal A breast cancer, we performed gene set enrichment analysis (GSEA) on breast cancer samples from the TCGA database, focusing on cases with high STC2 expression." (PMID 40006048, 2025). "Our findings support this, and we found that the expression of STC2 in human breast duct cancer cell line T-47D was about 900 times higher than that in normal breast epithelial cells, which may offer some insights into the classification and differentiation of breast cancer single cells." (PMID 39020010, 2024). "We further evaluated the connection between LncRNA MAFG-AS1, and STC2 using qRT-PCR for detecting the expression levels of LncRNA MAFG-AS1 and STC2 in breast cancer tissues and in adjacent normal breast tissues." (PMID 35513366, 2022). "Therefore, it may be inevitable to clarify the role of STC2 for the treatment of breast cancer." (PMID 37287492, 2021). "Ectopic expression of STC2, an inhibitor of PAPP‐A, compromised breast cancer cell proliferation and motility." (PMID 33788403, 2021). "STC2 is the target gene of HIF-1 and has been proved to be a prognostic marker of ovarian cancer, breast cancer, and kidney cancer." (PMID 34977159, 2021). "According to previous studies, both STC2 and BCL2 are estrogen-responsive genes that are upregulated in luminal breast cancers and correlate with a better prognosis 18-22." (PMID 31410192, 2019). "Finally, we analyzed STC2 gene expression using the GSE240671 dataset, which contains RNA sequencing data from breast cancer patients before and after neoadjuvant chemotherapy." (PMID 40006048, 2025). "STC2 upregulated Bax and cleaved PARP protein expression in two types of breast cancer cells." (PMID 35607324, 2022).
breast carcinoma (continued). "The experimental results indicated that EMT process could be inhibited by STC2 in a manner of regulating the expressions of PKC and Claudin-1, thereby inhibiting the breast cancer cells to migrate and invade." (PMID 37287492, 2021). "In breast cancer, BRCA1 gene may induce STC1 to express; STC1 and STC2 in tumor tissues indicate over expression in ER+ breast cancer cells, hormones is an essential element to regulate the expression of STC2." (PMID 37287492, 2021). "Based on these observations, we conclude that STC2 suppresses EMT to hinder cell migration and invasion via the PKC/Claudin-1-mediated signaling, which may be useful for breast cancer diagnosis and treatment." (PMID 25830567, 2015). "Increased STC2 phosphorylation was also found in the plasma of patients suffering from breast cancer, and, although both diseases are not related, they may share some key common intracellular proteins." (PMID 41155293, 2025). "Interestingly, the expression of STC2 was distinct between inflammatory and non-inflammatory estrogen receptor-positive breast cancer patients as assessed by metagene analysis." (PMID 34612765, 2021).
colorectal cancer (35 papers, 2013 to 2026). A primary or metastatic malignant neoplasm that affects the colon or rectum. "High expression of STC2 was significantly associated with poor prognosis, lymph node metastasis, distant metastasis, and advanced clinical stage in colorectal cancer patients." (PMID 41425852, 2025). "In colorectal cancer, the upregulated STC2 was associated with a poorer prognosis." (PMID 36998462, 2023). "STC2 over-expression in colorectal cancer may be associated with more aggressive tumor behavior including increased tumor invasion, higher histological grade, higher rate of nodal metastasis and increased incidence of lymphovascular and perineural invasions." (PMID 35096084, 2022). "Given the pressing need for better diagnostic markers and therapeutic targets in CRC, this study aims to explore the relationship between STC2 expression and colorectal cancer comprehensively." (PMID 40535801, 2025). "Overall, our findings suggest the METTL3/STC2 axis as a promising therapeutic target to combat drug resistance and metastasis in colorectal cancer." (PMID 40494964, 2025). "In accordance, luciferase assay demonstrated genetic manipulation of Sp1 alters STC2 promoter-mediated luciferase activity in a dose-dependent manner in colorectal cancer cells." (PMID 35501821, 2022). "In accordance, STC2 is upregulated in human colorectal cancer cells with resistance to oxaliplatin relative to their parental counterparts." (PMID 35501821, 2022). "The STC2 immunohistochemical expression was detected and evaluated in 60 cases of colorectal cancer tissue samples of formalin-fixed and paraffin-embedded blocks." (PMID 35096084, 2022). "As a secreted glycoprotein, STC2 has been detected in the sera of patients with colorectal cancer, gastric cancer, and laryngeal cancer." (PMID 35501821, 2022). "While the biological roles of STC2 under this condition require further investigation, it is generally believed high level of STC2 expression predicts poor prognosis of colorectal cancer patients." (PMID 35501821, 2022). "Only a few studies previously focused on the STC2 expression in colorectal cancer and most of these studies were experimental or focused on DNA analysis." (PMID 35096084, 2022). "Several studies showed similar results that STC2 levels were higher in colorectal cancer (CRC) tissues than normal tissues, which were related to tumor size, histological grade, lymph node metastasis, lymphatic invasion, and tumor depth." (PMID 34612765, 2021). "Studies have also found that STC2 regulates cell proliferation and apoptosis in colorectal cancer cells by activating the RAS/RAF/MEK/ERK pathway." (PMID 32906580, 2020). "In colorectal cancer, STC2 promoted the epithelial-mesenchymal transition of colorectal cells via AKT-ERK signaling pathway." (PMID 32296395, 2020). "The elevated level of STC2 was further validated among 77 cases of human colorectal cancer tissues (CCTs) compared with patients' autologous para-cancer colorectal mucosa tissues (PCTs) by IHC." (PMID 27662663, 2016). "Previous studies have shown that the expression of STC2 in colorectal cancer tissue was higher than in corresponding normal colorectal epithelial tissue." (PMID 23548070, 2013). "The expression of STC2 was significantly correlated with lymph node metastasis, lymphatic invasion, and distant metastasis of esophageal squamous cell cancer and colorectal cancer." (PMID 23548070, 2013). "The potential involvement of STC2 in colorectal cancer has begun to draw attention." (PMID 40535801, 2025). "Only few studies reported the role of STC2 in colorectal cancer." (PMID 40535801, 2025). "Few studies have covered the roles of STC2 in colorectal cancer." (PMID 40535801, 2025). "Furthermore, elevated STC2 levels are associated with invasiveness and metastasis in human tumours like ESCC, gastric cancer, colorectal cancer, RCC and neuroblastoma." (PMID 35501821, 2022).
colorectal cancer (continued). "To improve the diagnostic capacity of serum biomarkers for colorectal cancer (CRC), we introduced three novel indicators, namely, the C-X-C motif chemokine ligand 5 (CXCL5), stanniocalcin 2 (STC2), and chitinase 3 like 1 (CHI3L1) and assessed their performances in the detection of CRC." (PMID 35646113, 2022). "The genome-wise studies revealed higher STC2 mRNA levels in colorectal cancer than normal tissues." (PMID 35501821, 2022). "STC2 (top three)promotes EMT progression in colorectal cancer, inducing tumourigenesis." (PMID 36124841, 2022). "In addition to expression in cancer tissues, STC2 was detected in patient sera from several cancers including gastric cancer, colorectal cancer, and laryngeal cancer." (PMID 34612765, 2021). "For example, AGR3 has been shown to facilitate the stemness of colorectal cancer by regulating Wnt/β-catenin signaling; STC2 has been shown to be involved in resistance to treatment with EGFR tyrosine kinase inhibitors and to promote the progression of lung cancer by regulating JUN/AXL signaling." (PMID 33680908, 2020). "Ieta had detected high STC2 mRNA expression in colorectal cancer." (PMID 27662663, 2016). "In some malignant neoplasms, including esophageal squamous cell cancers, gastric cancers, colorectal cancers, and renal cell carcinomas, high expression of STC2 correlates with tumor progression and poor prognosis, which is consistent with our findings in LSCC." (PMID 24743310, 2014). "STC2 may serve as a potential therapeutic target and prognostic biomarker for colorectal cancer." (PMID 41696444, 2026). "However, STC2, its predicted target gene, has been revealed in published studies about its tumorigenesis in colorectal carcinoma, which implied that miR-4444-2 may regulate STC2 though a certain mechanism in CA." (PMID 32154160, 2020). "This study aims to elucidate the role of m6A modification in colorectal cancer (CRC), focusing on the effect of METTL3 on STC2 expression and its effects on cell proliferation, drug resistance and metastasis." (PMID 40494964, 2025). "For instance, Yuanet al. reported that elevated level of STC2 activates the PI3K/AKT pathway, leading to increased expression of the drug-resistant protein P-gp and enhanced resistance of colorectal cancer cells to oxaliplatin." (PMID 38477044, 2024). "We summarized STC2-mediated signaling pathways to involve in cancer EMT process, which is a pivotal step for colorectal cancer metastasis." (PMID 27662663, 2016). "The results suggest STC2 activates EMT process via two signaling pathways including PI3K/AKT and MEK/ERK in colorectal cancer cells." (PMID 27662663, 2016). "STC2 promotes occurrence and migration of colorectal cancer via the EMT process, because the elevated STC2 level and its clinicopathologic correlations widely exist in CRC tissues and serum samples." (PMID 27662663, 2016). "Clinical and pathological studies reveal that STC2 overexpression correlates to advanced tumor grade, tumor invasiveness, metastasis and poor prognosis in prostate cancer, ESC, gastric cancer, colorectal cancer and RCC." (PMID 24606961, 2014). "Moreover, STC2 also promotes the proliferation of tumour cells derived from ESCC, gastric cancer, colorectal cancer, nasopharyngeal carcinoma, etc.." (PMID 35501821, 2022). "Both mRNA and protein levels of STC2 are elevated in human colorectal cancer tissues comparing to the noncancerous counterparts." (PMID 35501821, 2022). "Further study revealed that STC2 promoted EMT and colorectal cancer migration." (PMID 34612765, 2021). "STC2 has been demonstrated to coregulate signaling of AKT and ERK in colorectal cancer cells." (PMID 32993096, 2020). "Chen's study revealed that STC2 promoted EMT and colorectal cancer migration." (PMID 32258098, 2019). "It remains unclear how STC2 regulates the epithelial-mesenchymal transition (EMT) process and colorectal cancer (CRC) development." (PMID 27662663, 2016).